PVT1 (Pvt1 oncogene)
Diseases named in the same sentence as PVT1 in open-access papers (continued):
Sharing a sentence is not in itself a finding about the gene and the disease.
melanoma (continued). "In addition to PVT1, lncRNA small nucleolar RNA host gene 5 (SNHG5) has emerged as a potential melanoma marker." (PMID 37629553, 2023). "Serum PVT1 levels were significantly higher in melanoma patients compared with age and sex-matched nonmelanoma and melanocytic nevus controls." (PMID 34670194, 2021). "Log-rank test of OS curves indicated that PVT1 expression was not related to OS, no matter in metastatic melanoma (p = 0.13) or in primary melanoma (p = 0.98)." (PMID 29244840, 2017). "In this study, by using deep-sequencing data and follow-up data in the Cancer Genome Atlas-Uveal melanomas (TCGA-UVM), we found that PVT1 expression is modulated by both DNA amplification and methylation and its high expression independently predicts poor OS in patients with primary uveal melanoma." (PMID 29244840, 2017). "Analysis of PVT1 expression in 24 melanoma tissues and 9 nonneoplastic nevi tissues revealed that PVT1 is significantly upregulated in melanoma tissues compared with nonneoplastic nevi tissues." (PMID 28265576, 2017). "All the results revealed that PVT1 is upregulated in melanoma tissues in comparation with nonneoplastic nevi tissues." (PMID 28265576, 2017). "Our results, combined with publicly available PVT1 expression data, revealed that PVT1 is upregulated in melanoma tissues compared with nonneoplastic nevi tissues." (PMID 28265576, 2017). "Serum PVT1 level is significantly increased in melanoma patients compared with age and gender-matched nonmelanoma controls with melanocytic nevus." (PMID 28265576, 2017). "In addition, a 2017 study observed upregulated PVT1 in melanoma tissues compared to age- and gender-matched non-neoplastic nevi tissues." (PMID 37629553, 2023). "Furthermore, we found that serum PVT1 level is significantly increased in melanoma patients in comparation with nonmelanoma controls with melanocytic nevus." (PMID 28265576, 2017). "To investigate whether melanoma tissues highly expressed PVT1 could be used as a noninvasive biomarker for melanoma, we collected serum from 51 melanoma patients before surgery and 47 age and gender-matched nonmelanoma controls with melanocytic nevus." (PMID 28265576, 2017). "Additionally, the previously reported oncogenic lncRNA in melanoma PVT1 was eliminated from this short list as no validation could be achieved." (PMID 40552742, 2025).
asthma (21 papers, 2017 to 2025). "For instance, lncRNA plasmacytoma variant translocation 1 (PVT1)regulates the proliferation of airway smooth muscle cells and release of IL-6 in thepatients suffering from severe asthma." (PMID 32520202, 2020). "We have mentioned in lncRNA plasmacytoma variant translocation (PVT1) that PVT1 regulates ASMCs proliferation in severe asthma." (PMID 33013382, 2020). "Conclusively, lncRNA PVT1-miR-15a-5p/miR-29c-3p-PI3K-Akt-mTOR axis was implicated in ozone-induced asthma development by promoting ASMC proliferation and Th1/Th2 imbalance." (PMID 33223504, 2020). "Through mediating E2F transcription factor 3 (E2F3) expression, lncRNA plasmacytoma variant translocation 1 (PVT1) is deemed to be correlated with the effects of α-asarone in the treatment of RSV-induced asthma." (PMID 31223533, 2019). "Dysregulation of PVT1 is also associated with breast and ovarian cancer, acute myeloid leukemia and Hodgkin’s lymphoma, vitiligo, and asthma." (PMID 31877167, 2019). "Here we attempted to uncover whether lncRNA PVT1-miRNA axis was implicated in the pathogenesis of ozone-induced asthma." (PMID 33223504, 2020). "Hence, this investigation was carried out to elucidate the association of lncRNA PVT1-led miRNA axes with ozone-induced asthma, which was conducive to clinical prevention and treatment of asthma." (PMID 33223504, 2020). "PVT1 is also associated with immune diseases like asthma, vitiligo, and several others." (PMID 31877167, 2019). "During ozone-induced asthma exacerbation, PVT1 activates the phosphatidylinositol 3-kinase (PI3 K)/AKT/mammalian target of rapamycin (mTOR) pathway by inhibiting the miR-15a-5p pathway, resulting in a reduced Th1/Th2 ratio that facilitates asthma progression." (PMID 40493320, 2025). "In chronic obstructive pulmonary disease patients, the PVT1 expression positively correlated with the GOLD stage and levels of TNF-α, IL-6, IL-8, and IL-17; PVT1 exacerbates the inflammation and cell-barrier injury during asthma by regulating miR-149." (PMID 33506021, 2021). "CD4+ T cell-derived Th1/Th2 imbalance is an initiating factor in ozone exacerbated asthma through PVT1-miR-15a-5p/miR-29c-3p signaling, and miR-15b-5p is considered a biomarker for identifying patients with asthma chronic obstructive pulmonary disease overlap." (PMID 34566492, 2021). "The distinct change of expression of lncRNA PVT1 was observed in patients with corticosteroid-sensitive severe asthma." (PMID 34970542, 2021). "Suppressing PVT1 expression also engendered a marked decrease of IL-6 level, which was reflective of abated inflammation in asthma." (PMID 33223504, 2020). "It seemed that PVT1 was promising in diagnosis of asthma (AUC=0.909) and in differentiating patients with acute asthma from asthma patients in remission stage (AUC=0.705)." (PMID 33223504, 2020). "Founded on the ceRNA theory, we suspected that PVT1 probably urged asthma progression by sponging miR-15a-5p and miR-29c-3p, two protective miRNAs in asthma." (PMID 33223504, 2020). "MiRNAs potentially sponged by PVT1 were predicted with usage of starbase software, and asthma-relevant miRNAs were measured in CD4+ T cells and ASMCs isolated from mice models." (PMID 33223504, 2020). "With regard to miR-29c-3p, which was down-regulated in asthma children, we found it effective in reversing the contribution of PVT1 to ASMC proliferation and viability." (PMID 33223504, 2020). "In conclusion, this investigation tentatively verified that ozone exacerbated asthma development by activating PVT1-miR-15a-5p/miR-29c-3p signaling, which motivated Th1/Th2 imbalance of CD4+ T cells and urged excessive proliferation of ASMCs." (PMID 33223504, 2020). "PVT1 is decreased in patients with corticosteroid-sensitive non-severe asthma and increased in patients with corticosteroid-insensitive severe asthma." (PMID 30941157, 2019).
asthma (continued). "When PVT1 was targeted with siRNAs in ASMCs from patients with severe asthma, the FCS plus TGF-β– and dexamethasone plus FCS plus TGF-β–induced c-MYC expression was returned to basal levels." (PMID 27484035, 2017). "When PVT1 was targeted with siRNAs in ASMCs from patients with severe asthma, the FCS plus TGF-β– and dexamethasone plus FCS plus TGF-β–induced PVT1 expression was returned to basal levels." (PMID 27484035, 2017). "It was thus speculated that PVT1-miRNA axis might participate in ozone-induced asthma development by activating PI3K/Akt/mTOR signaling." (PMID 33223504, 2020). "Serum level of PVT1 also went up significantly in asthma patients when compared with healthy controls (P<0.05), and patients with acute asthma revealed higher PVT1 expression than asthma patients in remission stage (P<0.05)." (PMID 33223504, 2020). "This investigation attempted to elucidate whether lncRNA PVT1-led miRNA axes participated in aggravating ozone-triggered asthma progression." (PMID 33223504, 2020). "Additionally, PVT1 seemed promising in diagnosis of asthma, with favorable sensitivity (i.e. 0.844) and specificity (i.e. 0.978)." (PMID 33223504, 2020). "However, PVT1 knockdown increased BrdU incorporation in ASMCs from patients with severe asthma when they were exposed to dexamethasone before stimulation with FCS plus TGF-β (P < .01 vs dexamethasone plus FCS plus TGF-β)." (PMID 27484035, 2017). "Furthermore, FCS plus TGF-β led to an approximately 3-fold increase (P < .01 vs unstimulated control ASMCs) in PVT1 expression, which reached a plateau at 3 hours in ASMCs from patients with severe asthma and remained increased at 24 hours." (PMID 27484035, 2017). "Furthermore, in ASMCs from patients with severe asthma, dexamethasone increases PVT1 expression, and inhibition of this with siRNAs results in an increase in FCS plus TGF-β–induced cellular proliferation through targeting of the transcription factor c-MYC." (PMID 27484035, 2017). "It is speculated that PVT1 may be a new potential target for the treatment of asthma." (PMID 34635022, 2021). "Upregulated lncRNA PVT1 could inhibit the expression of miR-149 in bronchial epithelial cells, promote airway inflammation and destroy the cellular barrier, thus accelerating the development of asthma." (PMID 34635022, 2021). "Of note, PVT1, which contained a genomic region indicative of high cancer risk, was conjectured to involve in ozone-caused asthma progression, allowing for that PVT1 expression was strongly correlated with ASMC function and Th1/Th2 balance of ozone-treated asthma mice models." (PMID 33223504, 2020). "Of note, expression of lncRNA PVT1 was dramatically lowered in ASMCs that were exposed to anti-asthmatic drugs, providing a hint that PVT1 might be associated with ASMC dysfunction underlying asthma etiology." (PMID 33223504, 2020). "In addition, reduced expression of PVT1 was reported in PB cells of relapsing-remitting multiple sclerosis patients compared with healthy subjects and a role for PVT1 has been reported in the inflammatory processes involved in asthma and septic acute kidney injury." (PMID 32228602, 2020). "Notably, PVT1 has a great potential to regulate ASMCs proliferation in severe asthma and may act as a predictor of the ASMCs phenotype." (PMID 33013382, 2020). "Furthermore, dexamethasone alone increased PVT1 expression in ASMCs from patients with severe asthma (approximately 4-fold, P < .001), and when these cells were subsequently stimulated with FCS plus TGF-β, an even greater increase in expression was observed (approximately 8-fold, P < .001)." (PMID 27484035, 2017). "Of those lncRNAs that were expressed in ASMCs from asthmatic patients, only PVT1 was found to be decreased in expression in the patients with corticosteroid-sensitive nonsevere asthma and increased in expression in patients with corticosteroid-insensitive severe asthma (see Tables E10 and E11)." (PMID 27484035, 2017).
asthma (continued). "In ASMCs from patients with severe asthma, TGF-β plus FCS not only induces IL6 mRNA expression and protein release but also PVT1 expression." (PMID 27484035, 2017). "PVT1 was also involved in proliferation and IL-6 release in airway smooth muscle (ASM) from patients with severe asthma." (PMID 29186897, 2017). "We also observed a significant change in lncRNA expression, yet the expression of only one lncRNA (PVT1) is decreased in patients with corticosteroid-sensitive nonsevere asthma and increased in patients with corticosteroid-insensitive severe asthma." (PMID 27484035, 2017). "In ozone-induced exacerbation of asthma, PVT1 activates the asthma-related phosphatidylinositol 3-kinase (PI3K)/AKT/mammalian target of rapamycin (mTOR) pathway by inhibiting miR-15a-5p, leading to a decrease in Th1/Th2 ratio, thereby promoting the progression of asthma." (PMID 35794862, 2022). "Despite hidden linkages between PVT1 and airway remodeling/inflammation, it remained ambiguous whether PVT1 indeed disrupted normal activity of ASMC and CD4+ T cell by sponging protective miRNAs in asthma." (PMID 33223504, 2020). "However, the FCS plus TGF-β–induced reduction of PVT1 expression in ASMCs from patients with nonsevere asthma returned to basal levels in the presence of dexamethasone (P < .01)." (PMID 27484035, 2017). "FCS plus TGF-β did not change the expression of PVT1 up to 24 hours in ASMCs from healthy subjects, whereas at 24 hours, there was a significant reduction in the expression of PVT1 in ASMCs from patients with nonsevere asthma (P < .01 vs unstimulated control ASMCs)." (PMID 27484035, 2017). "Interestingly, PVT1 was significantly increased in patients with severe asthma and decreased in patients with non-severe asthma." (PMID 29186897, 2017).
Burkitt lymphoma (21 papers, 2008 to 2024). A rare form of malignant mature B-cell non-Hodgkin lymphoma. "Plasmacytoma variant translocation 1 (PVT1) is a lncRNA encoded by Pvt1 oncogene locating at chromosome 8q24.21, which was first identified in human cancer translocations as a recurrent breakpoint in Burkitt’s lymphoma." (PMID 39376555, 2024). "The first lncRNA gene, found in Burkitt’s lymphoma translocations, was Plasmacytoma variant translocation 1 (PVT1)." (PMID 35011637, 2021). "As an oncogenic lncRNA, plasmacytoma variant translocation 1 (PVT1) was initially reported as a recurrent breakpoint in Burkitt's lymphoma." (PMID 34518442, 2021). "Plasmacytoma variant translocation 1 (PVT1) was the first linear lncRNA identified in human Burkitt's lymphoma." (PMID 32194627, 2020). "Plasmacytoma variant translocation 1 (PVT1) is the first lncRNA gene discovered in Burkitt’s lymphoma, and its lncRNA that has been reported to play a role in promoting tumor progression." (PMID 33109235, 2020). "Plasmacytoma variant translocation 1(PVT1) was the first lncRNA gene identified in human Burkitt's lymphoma as a recurrent breakpoint." (PMID 32257946, 2020). "Similarly, a common chromosome eight breakpoint mutation in Burkitt’s lymphoma was linked to the PVT1 locus in a mouse model, implicating PVT1 in disease tumorigenesis." (PMID 31379598, 2019). "Translocations within c-Myc or PVT1, which cause the overexpression of these two oncogenes compared to healthy cells, are characteristics associated with B cell malignancies including Burkitt Lymphoma (BL), AIDs, Non-Hodgkin lymphoma, mouse plasmacytoma (Pct) and multiple myeloma (MM)." (PMID 23887658, 2013). "In Burkitt's lymphoma, the so-called 'variant' translocations, T(2:8) or T(8:22), found in about 20% of such tumors, juxtapose immunoglobulin kappa or lambda light chain genes to the PVT1 locus." (PMID 18194563, 2008). "PVT1 is closely located in the genome to the MYC gene, an universal amplifier of transcription associated with e.g. leukaemia or Burkitt lymphoma." (PMID 38384455, 2024). "Previous studies showed that Pvt1 binds Cdkn1a and miR-149-3p to suppress their activity in primary chondrocytes and Burkitt lymphoma Rajit cells, respectively." (PMID 34364390, 2021). "In another study, knockdown of PVT1 inhibited the proliferation of Burkitt lymphoma cells by arresting the cells in G0/G1 phase which was associated with a reduction of MYC expression and alterations in the expression of cell cycle-associated genes." (PMID 33134177, 2020). "PVT1 is an oncogene identified in Burkitt's lymphoma, while Adapt33 is a stress‐induced transcript upregulated in response to apoptotic stimuli." (PMID 32602581, 2020). "PVT1 was identified as a locus co-amplified with MYC in human Burkitt's lymphomas and found to be a MYC activator." (PMID 21814516, 2011). "The gene encoding PVT1 is located on the long arm of chromosome 8q24 in a region about 55 kb distal to the MYC gene and, very similar to MYC, is frequently involved in translocations occurring in Burkitt lymphoma." (PMID 33134177, 2020). "Chromosome translocation was the first identified abnormality of PVT1 in tumors (Burkitt lymphoma)." (PMID 31601234, 2019).
diabetes (21 papers, 2011 to 2025). "Another lncRNA, Plasmacytoma variant translocation 1 (PVT1), plays a critical role in regulating apoptosis, inflammation, and other processes in various diabetes-related complications." (PMID 39498440, 2024). "Increased expression of lncRNA PVT1 activates the oxidative stress and β-cell apoptosis; however, its silencing enhances the insulin secretory capacity, which classify the PVT1 as a diabetes-associated lncRNA." (PMID 37670346, 2023). "rs13447075 is situated in the coding portion of one of the transcript variants of PVT1, indicating an association of PVT1 in mediating susceptibility to ESRD attributable to diabetes." (PMID 29915562, 2018). "PVT1, one of the more studied lncRNAs, is closely associated with diabetes." (PMID 36874406, 2023). "In fact, Pvt1 has been already associated to metabolic disorders such as diabetes." (PMID 30649422, 2019). "In addition, the increased expression of lncRNA PVT1 in diabetic OA cartilage is also associated with Mankin score and reduced expression of type II collagen by negatively interacting with miR-146a, increasing the productions of inflammatory cytokines, and activating TGFβ/SMAD4 signaling pathway." (PMID 34874225, 2021). "With advancements in detection and application technology, PVT1 shows potential as a non-invasive biomarker and therapeutic target in the development of new treatments for diabetes." (PMID 39498440, 2024). "In order to further reveal the differential regulation of lncRNA in type 1 diabetes, we extracted one common and differentially expressed lncRN, as known as lncRNA PVT1, which has been proved to play an important role in exosomes and diabetes." (PMID 36440209, 2022). "The lncRNA plasmacytoma variant translocation 1 (PVT1) has been implicated in cancer, diabetes and septic acute kidney injury." (PMID 30126849, 2018). "Then, we generated mice with podocyte-specific deletion of PVT1 (Nphs2-Cre/Pvt1flox/flox) and confirmed that the deletion of PVT1 suppressed podocyte mitochondrial dysfunction and inflammation in addition to ameliorating diabetes-induced podocyte injury, glomerulopathy, and proteinuria." (PMID 39349450, 2024). "To date, only PVT1 expression has been found to be modulated with autophagy in diabetes." (PMID 36899946, 2023). "So far, PVT1 is the only reported lncRNA which is regulated by autophagy in diabetes." (PMID 30693021, 2018). "Findings of expression in different cell types of the kidney provided preliminary evidence that PVT1 may influence metabolic dysregulation in this tissue preceding the development of renal failure in diabetes." (PMID 21526116, 2011). "However, the deepgoing regulation of lncRNA PVT1 in the diabetic cataract (DC) is still unclear." (PMID 31755246, 2019). "Diabetes positively regulates APP (4 references; q = 0.00015), NLRP3 (19 references; q = 0.00168), and PVT1 (4 references; q = 0.00755), while negatively regulating CYP2C19 (14 references; q = 0.00372), suggesting its influence on pathways related to inflammation, immune response, and metabolism." (PMID 40881172, 2025). "The consistent directionality and statistical significance observed in the regulation of APP, NLRP3, PVT1, and CYP2C19 suggest the possibility of a Diabetes → gene → HNSCC pathway, in which diabetes-related gene alterations may contribute to HNSCC pathogenesis." (PMID 40881172, 2025). "Also, RNA-FISH combined with immunofluorescence reveled that Pvt1 was found in both the nucleus and cytoplasm and that its expression increased in the podocytes of STZ mice when compared with CTL mice at 20 weeks after induction of diabetes." (PMID 39349450, 2024). "While the relationship between PVT1 and certain forms of cancer has been firmly established, the role that this gene may play in mediating the development of kidney disease in diabetes is presently not known." (PMID 21526116, 2011).